OCLN (occludin)
Diseases named in the same sentence as OCLN in open-access papers (continued):
Sharing a sentence is not in itself a finding about the gene and the disease.
tumor (continued). "Collectively, these results indicate great potential for OCLN as a multipotent therapeutic target to inhibit tumour angiogenesis and progression in BLCA." (PMID 35224833, 2022). "OCLN exerted a proangiogenic effect on BLCA cells and regulated tube formation by endothelial cells cultured with CM derived from 5637 and T24 cells by altering IL8 levels, indicating that OCLN promotes tumour neovascularization through IL8." (PMID 35224833, 2022). "Tube formation assays confirmed that Stattic blocked the proangiogenic effect of OCLN overexpression, indicating that STAT3 was involved in OCLN‐modified modulation of tumour angiogenesis in BLCA." (PMID 35224833, 2022). "A few studies have also shown roles of OCLN in modulating tumour angiogenesis and tube‐forming activity for tumour invasion." (PMID 35224833, 2022). "Occludin is a transmembrane tight junction protein that directly interacts with Claudins and actin and plays a role in barrier regulation and tumour suppression." (PMID 34162433, 2021). "Sp1 is involved in the modulation of the activities of the occludin promoter by Krüpple-like factor 4 in the blood-tumor barrier." (PMID 33827415, 2021). "Whereas higher expression of SOX10, OCLN, ACSL4, XIAP, and ERCC5 was associated with a lower risk of death from the tumor (HR < 1)." (PMID 33153038, 2020). "We noted that CLG reduced the expression of various epithelial markers and up-regulated the expression of Occludin and E-cadherin in both basal and TGFβ-stimulated tumor cells." (PMID 33027960, 2020). "It is interesting to note that in the overwhelming majority of cases, occludin abundance is inversely correlated with tumor progression." (PMID 33291824, 2020). "The western blot assay also showed that the expression of Occludin and Claudin in tumor and liver tissues were changed toward their normal levels." (PMID 30651572, 2019). "The expression of exogenous occludin suppresses tumor growth in nude mice of Raf1-transformed rat salivary gland epithelial cells." (PMID 31783547, 2019). "PI3K/Akt pathway can activate Snai1 and slug expression that has been correlated with EMT and invasive tumor types through repression of E-cadherin and occludin expression mediated by Snai1/SMAD3/SMAD4 complex." (PMID 31798766, 2019). "Claudin-1 and occludin modulate intestinal-mucosal structure and function, and integrate diverse processes, such as gene transcription, tumor suppression, cell proliferation, and cell polarity." (PMID 30360365, 2018). "The BTB hinders hydrophilic molecules diffusing by paracellular transport into tumor tissues by endothelial TJ composed of integral membrane proteins (claudins, occludin, and junctional adhesion molecules) and intracellular proteins (ZO-1 and cingulin)." (PMID 29467620, 2018). "Especially claudin-1 and occludin integrate diverse processes, such as gene transcription, tumor suppression, and cell proliferation." (PMID 30360365, 2018). "Classical epithelial markers, such as CDH1 and occludin (OCLN), were downregulated in the tumor bud samples compared to IEC and CCPT." (PMID 28687755, 2017). "The expression of PKCα, ZO-1, occludin and claudin-5 in tumor microvessel segments was detected by Real-time PCR assay." (PMID 29311822, 2017). "For example, the epithelial markers CDH1 and OCLN are down-regulated in tumor buds compared to the cancer cells in the center of the primary tumor, and up-regulated in the stroma of tumor budding compared to the stroma of regular cancer cells." (PMID 28687755, 2017). "In primary tumours, the decreased epithelial markers such as E-cadherin, occludin, cytokeratin and the increased mesenchymal markers including N-cadherin, vimentin, snail, slug can promote the tumour invasion and metastasis." (PMID 28548934, 2017). "In the areas of overexpression, occludin was detected in the tumor cells both at the lateral plasma membrane and at the apical cell border." (PMID 29163827, 2017).
tumor (continued). "Immunohistochemical staining for E-cadherin, Occludin, Vimentin, and N-cadherin showed that PTL increased E-cadherin and Occludin levels, whereas it decreased Vimentin and N-cadherin levels in tumor tissues." (PMID 29050271, 2017). "Histamine significantly decreased the protein levels of ZO-1, occludin, and claudin-5 in endothelial and tumor cells." (PMID 27121317, 2016). "The expression of HSF2, ZO-1, occludin and claudin-5 in tumor microvessel segments was detected by Real-time PCR assay." (PMID 26078353, 2015). "These repressors also trigger the EMT program by repressing genes encoding claudins, cytokines, integrins, mucins and occludin proteins, thereby promoting EMT 27, and pre-disposing tumour cells to invasion and metastasis." (PMID 25215932, 2014). "Snail can negatively regulate a number of tumor suppressors including E-cadherin, claudins, and occludin, by binding to E-boxes in the promoter region." (PMID 22857708, 2012). "Occludin and claudins are components of tight junctions and their expression progressively decreases both in NC and tumor cells." (PMID 21433221, 2011). "Intriguingly, overexpression of occludin in a variety of tumor cells sensitized the cells to apoptosis inducing agents and occludin negative clones showed reduced ability to extrude apoptotic cells from MDCK monolayers." (PMID 20003227, 2009). "Claudins and occludin are tight junctional proteins whose expression has been studied in various tumour types, and tentatively correlated with tumour proliferation as a result of a mechanism involving the activity of matrix metalloproteinases." (PMID 19696947, 2009). "Tight junction (TJ) proteins, such as Junctional Adhesion Molecule-A (JAM-A), claudins, and occludin, play increasingly recognized roles in cancer biology beyond their structural functions, influencing tumour proliferation, invasion, metastasis and therapy resistance." (PMID 41681980, 2026). "Based on all these findings, it appears that reduced occludin expression may constitute a critical feature of ominous prognosis in various tumor entities that could be clinically useful." (PMID 40173205, 2025). "Firmicutes upregulate tight junction proteins (e.g., occludin, ZO-1), preventing microbial translocation and systemic inflammation, which could otherwise suppress anti-tumor responses." (PMID 40364844, 2025). "Furthermore, Firmicutes reinforce gut barrier integrity by upregulating tight junction proteins such as occludin and ZO-1, thereby preventing microbial translocation and systemic inflammation, both of which are known to suppress anti-tumor responses." (PMID 40364844, 2025). "As TGF-β levels rise, EMT leads to epithelial tumor cells losing adhesion, polarity, and tight junctions by reducing tight junction proteins such as Zonula Occludens-1, E-cadherin, and Occludin, thus acquiring a highly migratory and invasive mesenchymal phenotype." (PMID 40722739, 2025). "Reduced occludin expression has been linked to cancer progression in individual tumor types, but a comprehensive and standardized analysis across human tumor types is lacking." (PMID 40173205, 2025). "Alcian blue and immunohistochemical staining for MUC2, ZO-1, and occludin expression in tumour tissues revealed increased mucin layer-related and tight junction protein expression in the intestinal wall, which strengthen the intestinal barrier, in the combined group." (PMID 38245554, 2024). "Suppression of fibronectin, vimentin, N-cadherin, MMP-9, MMP-2, twist, and snail.↑ Epithelial markers E-cadherin and Occludin levels.↓ Migratory and invasive potential of tumor cells by reversing epithelial-to-mesenchymal transition (EMT). ↓ PI3K/Akt/mTOR activation." (PMID 38611719, 2024). "Moreover, the methylation level of OCLN was increased with age, tumor grade, clinical stage and N stage." (PMID 37809090, 2023). "Moreover, the methylation level of OCLN was positively correlated with age, clinical stage, and tumor grade level." (PMID 37809090, 2023).
tumor (continued). "Occludin (OCLN) is an important tight junction protein that regulates cytoskeletal remodeling, it is reported to be aberrantly expressed in many malignant cancers during tumour progression and to contribute to apoptosis and metastasis." (PMID 35224833, 2022). "In addition, we showed that STAT3 participates in OCLN‐mediated regulation of tumour angiogenesis in BLCA." (PMID 35224833, 2022). "As tumour angiogenesis plays an important role in the occurrence, development and metastasis of many tumours, our study expands the in‐depth knowledge of the possible effects of OCLN and proposes the basic principle of targeting OCLN to suppress angiogenesis in the treatment of metastatic tumours." (PMID 35224833, 2022). "BLCA is a highly vascularized tumour, and we investigated whether OCLN was involved in the development of BLCA by regulating tumour angiogenesis." (PMID 35224833, 2022). "The role of Claudin 1 and Occludin in tumor progression and metastasis remained controversial." (PMID 33613746, 2021). "While a decrease in occludin, zonula occludens, and claudin-5 expression was measured in the sedentary mice, an increase in claudin-5 expression and unchanged occludin and zonula occludens levels were found in the exercising mice 48 h post tumor injection." (PMID 31936342, 2020). "Reduction in the abundance of representative proteins of tight junctions (occludin and ZO-1), gap junctions (connexin-43) and desmosomes (desmoglein-2) was established in 3D tumor models compared to monolayer, with the most pronounced suppression in collagen hydrogel." (PMID 33291824, 2020). "Of course, future studies will need to establish whether the performance of the serum occludin level as a clinical biomarker varies between different pathological types of tumor." (PMID 32884584, 2020). "However, so far, there is no report showing that the knockout of any tight junction component by itself can spontaneously lead to tumor formation, although, hyperplasia of the gastric epithelium has been observed in an occludin knockout model." (PMID 33202923, 2020). "Strikingly, we found that the TJ proteins CLDN1 and OCLN showed an abnormal distribution within the tumor tissue, appearing clumpy and aggregated compared to the typical linear pattern lining the cellular membranes observed in the surrounding nontumorous tissue." (PMID 29538454, 2018). "However, other TJ proteins such as occludin and claudin-11 have been detected in CAFs of other tumor types." (PMID 29134439, 2018). "However, the expression of occludin was altered, as the protein's distribution was heterogeneous in tumor cells, with strong accumulation in the lateral walls of the cells as well as apically, rather than the apical distribution in normal cells." (PMID 29163827, 2017). "For example, occludin was shown to inhibit Raf-1 signaling which induces tumor growth." (PMID 27547510, 2016). "Experts who support the tumor suppressor gene hypothesis demonstrated that NKX2.1 could decrease the expression of occludin, which is a group of proteins localized to and regulating intercellular junctions, thus inhibiting the metastasis of malignant cells." (PMID 25478793, 2014). "However, given these functional indications of a tumor-relevant role of reduced occludin expression, the available information on the prevalence and clinical relevance of reduced occludin expression in clinical tumor tissue samples is sparse and partly contradictory." (PMID 40173205, 2025). "According to previous reports, tumour cells generally secrete large amounts of angiogenic factors into the extracellular matrix, promoting the formation of new blood vessels and tumour metastasis, which provides further support for the regulation of tumour angiogenesis by OCLN in BLCA." (PMID 35224833, 2022).
tumor (continued). "We focused on the role of STAT4 as a transcription factor in tumour angiogenesis and sought to explore whether OCLN mediated the transcription of IL8 via STAT4 as an approach to further verify the role of STAT4 in OCLN‐mediated regulation of IL8 expression in BLCA angiogenesis." (PMID 35224833, 2022). "Pearson's correlation analysis revealed that the preoperative serum occludin level was significantly positively correlated with the extent of the preoperative PTBE as measured by the vertical distance from the outer edge of the maximal edema zone to the tumor boundary (r = 0.78, P < 0.0001)." (PMID 32884584, 2020). "Immunohistochemical staining for E-cadherin, Occludin, Vimentin, and N-cadherin showed that apigenin treatment increased E-cadherin and Occludin levels, whereas it decreased Vimentin and N-cadherin levels, in both the membranes and cytoplasm of tumor cells as compared to untreated cells." (PMID 27203387, 2016). "Thus, we hypothesize that the elevated expression of WDR66 in ESCC may promote EMT through an up-regulation of vimentin expression and a down regulation of occludin and cohesion of the tumor tissue." (PMID 23514407, 2013). "SPIOCA gavage fortified intestinal barrier integrity-evidenced by elevated ZO-1, ZO-2, Occludin and Claudin-1 expression-and potentiated antitumor immune-cell infiltration, specifically by CD8+ T cells and dendritic cells, into the tumor microenvironment." (PMID 41660285, 2025). "Upregulate ZO-1, occludin, CD8 CTLs, ATP, and glucose of tumor-infiltrating lymphocytes; downregulate TNF-α, IL-1β, and PD-1." (PMID 38068759, 2023). "IHC staining of junctional proteins showed that the immunofluorescence of Claudin-5, VE-Cadherin, Occludin, and JAM-A persisted during 7–21 dpi at both tumor core and margin." (PMID 37582846, 2023). "In lung cancer, downregulation of OCLN inhibits activation of the AKT/PI3K signalling pathway and cell proliferation, thus increasing tumour apoptosis in vitro and in vivo." (PMID 35224833, 2022). "Mechanistically, OCLN knockdown inhibited IL8 expression and then reduced p‐STAT3 levels to interrupt tumour angiogenesis." (PMID 35224833, 2022). "Results show there was a significant increase in Occludin and Claudin‐1 in CPE cultures relative to co‐cultures of CPE and tumor cells." (PMID 33635590, 2022). "The analysis of tumor tissue by immunohistochemistry showed a high expression of tight junction proteins PARD3, TJP2, and occludin (OCLN) in subcutaneous tumors formed by Nrp2−/− CRC organoids." (PMID 35158941, 2022). "Corylin increased the levels of the colon tight junction markers ZO-1, claudin, and occludin in CAC mice by repairing TLR4 signaling and decreasing the phosphorylation of p38 and downregulation of inflammasome genes, thus affecting tumor progression." (PMID 35269806, 2022). "All these markers except sIL-6Rα, OCLN, STAT1 and STAT3, are upregulated in tumor samples compared to controls." (PMID 33846436, 2021). "The effective regulation by SPG-56 of the expression of metastasis-related proteins MMP2, MMP9, VEGF, Occludin, Claudin and STAT3 further confirmed the inhibition by SPG-56 of tumor metastasis." (PMID 30651572, 2019). "We found that HCV RNA suppression in the tumor correlates with disruption of the typical linear distribution of two major HCV-entry cofactors, claudin-1 (CLDN1) and occludin (OCLN), which mediate viral entry into hepatocytes." (PMID 29538454, 2018). "Increased OCLN and decreased BMP2 expression inhibit the epithelial-mesenchymal transition (EMT), an important stage in tumor cell invasion of tissues." (PMID 28755312, 2017). "In other systems, miR-18a has been shown to increase the permeability of the blood–tumor barrier via RUNX1-mediated down-regulation of the tight junction-related proteins ZO-1, occludin and claudin-544." (PMID 27767041, 2016).
tumor (continued). "Down-regulation of E-cadherin, occludin, claudin 3, 4, 7 as well as up-regulation of the mesenchymal genes and SNAI2 is in line with the features described in claudin-low tumor samples." (PMID 22044755, 2011). "The intestinal and tumor microbiome influences BBB permeability, and in the absence of normal intestinal flora, BBB permeability is significantly higher, which is the result of reduced expression of the tight junction proteins occludin and claudin-5." (PMID 39940760, 2025). "Another study found that glabridin inhibited EMT in breast cancer cells by upregulating E-cadherin and occludin, while downregulating vimentin, E-box-binding zinc finger protein 1 (Zeb1), and other critical EMT markers, thereby exerting a controlling effect on tumor invasion and metastasis." (PMID 39723390, 2024). "Thus, tumor cells subjected to EMT show a series of molecular changes characterized by decreased expression of epithelial markers, as E-cadherin, ZO-1 and occludin, and increased expression of mesenchymal markers as N-cadherin, vimentin and fibronectin." (PMID 36769105, 2023). "Further quantification of the area fraction ratio of protein over blood vessel (CD31) suggested that the relative protein coverage ratio for Claudin-5, VE-Cadherin, Occludin, and JAM-A was comparable at the tumor core, margin, and contralateral side during 7–21 dpi." (PMID 37582846, 2023). "Therefore, this study focused on the biological mechanism of OCLN in BLCA angiogenesis and provides potential targets for tumour treatment." (PMID 35224833, 2022). "Furthermore, OCLN promoted the transcription of IL8 through STAT4, ultimately contributing to tumour vascular remodelling and BLCA progression." (PMID 35224833, 2022). "Furthermore, OCLN overexpression enhanced the activity of the IL8/STAT3 signalling pathway by activating STAT4, ultimately contributing to tumour vascular remodelling and metastasis." (PMID 35224833, 2022). "The postoperative serum occludin level was not significantly correlated with the tumor diameter (r = 0.104, P = 0.449)." (PMID 32884584, 2020). "Therefore, occludin expression was analyzed in more than 16,000 tumor tissue samples from 148 different tumor types and subtypes as well as 76 non-neoplastic tissue categories by immunohistochemistry (IHC) in a tissue microarray (TMA) format in this study." (PMID 40173205, 2025). "The authors of these studies concluded from their findings, however, that occludin may not exert a direct tumor promoting role in theses tumors." (PMID 40173205, 2025). "Additionally, changes in claudin-2, -4, and -7 and other TJ proteins, such as ZO-1 and occludin, were found in SCC of the skin, but the association between claudin expression and tumor characteristics has not been analyzed so far." (PMID 36232536, 2022). "Indeed, we observed that the permeability and MVD of pulmonary capillaries were significantly increased in the tumor-bearing mice injected with MDA-MB-231 and CAFs (MDA-MB-231/CAFs shNC) before lung metastasis, and the expressions of ZO-1 and Occludin were decreased." (PMID 36438499, 2022). "Simultaneously, expression of TJ markers in tumor and normal squamous epithelial tissues revealed from both semiq-RTPCR and qPCR significant (p < 0.001) down regulation of ZO-1 (3.7-fold), CLDN-1 (2.9-fold), CLDN-7 (3.8-fold), OCLN (1.6-fold) and E-cadherin (2.3-fold) transcripts." (PMID 34316331, 2021). "Notably, the serum occludin level was related only to the degree of brain edema and not to the size of the tumor." (PMID 32884584, 2020). "Our observation of an elevated level of serum occludin suggests that a low content of occludin within a tumor may, at least in part, be due to the degradation of occludin rather than downregulated expression." (PMID 32884584, 2020). "However, the preoperative serum occludin level was not significantly correlated with the diameter of the tumor (r = 0.222; P = 0.103)." (PMID 32884584, 2020).